FTO (FTO alpha-ketoglutarate dependent dioxygenase)
Diseases named in the same sentence as FTO in open-access papers (continued):
Sharing a sentence is not in itself a finding about the gene and the disease.
itch (1 paper, 2025). "Therefore, we demonstrated that the gut microbiota is a key initiator of chronic itch via its effects on FTO-dependent m6A modification of MRGPRF expression." (PMID 40289281, 2025).
lentivirus infection (1 paper, 2023). Virus diseases caused by the Lentivirus genus. "Supported by CLIP of demethyltransferases showing FTO but not ALKBH5 bound with m6A site on Spi2a, we overexpressed FTO in BMDMs using lentivirus infection for further investigations." (PMID 36864027, 2023).
lymphoid leukemia (1 paper, 2025). A malignant lymphocytic neoplasm of B-cell or T-cell lineage involving primarily the bone marrow and the peripheral blood. "While the m6A demethylases FTO and ALKBH5 are recognized for their crucial roles in various cancers, their impact on lymphoid leukemia remains uncertain." (PMID 40435251, 2025).
male infertility (1 paper, 2023). The inability of the male to effect fertilization of an ovum after a specified period of unprotected intercourse. "In addition, we identified two functional mutations of FTO in male infertility patients, resulting in truncated FTO protein and increased m6A modification in vitro." (PMID 37146971, 2023). "We also identified two functional variants of FTO in oligospermia and NOA patients, which had a potential pathogenic effect on male infertility." (PMID 37146971, 2023). "Our research indicates a different role of FTO in the male reproductive system, which suggests a potential strategy for treating male infertility." (PMID 37146971, 2023). "Nevertheless, because activation of FTO might trigger negative effects in cancers, further well-established studies are needed to validate the potential therapeutic effect of FTO on male infertility." (PMID 37146971, 2023).
malignant glioma (1 paper, 2025). A grade III or grade IV glioma arising from the central nervous system. "Collectively, these data strongly indicate that FTO is downregulated in malignant glioma and that its low expression is a marker of poor prognosis, suggesting a tumor-suppressive role." (PMID 40970086, 2025).
mastitis (1 paper, 2024). Inflammation of breast tissue during lactation or postpartum due to an obstructed duct or infection. "This study supports the association of FTO with S. aureus mastitis at the individual level within dataset one." (PMID 38271969, 2024). "The initial findings on the function of RMRGs in S. aureus mastitis and the role of FTO in this biological process have the potential to partially elucidate the molecular mechanisms responsible for S. aureus mastitis in bovine." (PMID 38271969, 2024). "The m6A modification gene FTO showed significant effects on the expression of m6A and other RMRGs (such as NSUN2, CPSF2, and METTLE), indicating complex co-expression relationships among different RNA modifications in the regulation of bovine S. aureus mastitis." (PMID 38271969, 2024).
metastasis (1 paper, 2022). The spread or migration of cancer cells from one part of the body (where they first appeared) to another. "Moreover, we found the level of m6A was negatively relative with FTO mRNA expression in the tumor and liver metastasis tumor." (PMID 35064107, 2022).
metastatic colorectal cancer (1 paper, 2023). "This will lead to future clinical trials targeting FTO as a potential therapeutic strategy in the treatment of metastatic colorectal cancer." (PMID 36874096, 2023).
metastatic prostate carcinoma (1 paper, 2024). A carcinoma that arises from the prostate gland and has spread to other anatomic sites. "Next, it was found that METTL3 expression was decreased and FTO expression was increased in the metastatic prostate cancer samples." (PMID 38384328, 2024).
metastatic tumors (1 paper, 2024). "However, FTO expression levels did not distinguish between primary and metastatic tumors." (PMID 38270643, 2024).
mucositis (1 paper, 2025). Mucositis is inflammation and damage of the mucous membranes lining the mouth and other parts of the gastrointestinal (GI) tract. "On the “eraser” side, FTO has emerged as a radiosensitization target: genetic and pharmacologic FTO blockade increased DNA damage (reduced RAD51 foci, impaired HR) and improved tumor control by radiotherapy in HNSCC models—without exacerbating mucositis—indicating a widened therapeutic window." (PMID 41280938, 2025).
muscular atrophy (1 paper, 2023). The loss of muscle tissue due to inactivity or disease. "In addition to R-2HG, other FTO inhibitors (or m6A activators), such as Meclofenamic acid, N-(5-Chloro-2,4-dihydroxyphenyl)-1-phenylcyclobutanecarboxamide, as well as some small molecules, also have potential in anti-muscular atrophy effect, and are worth verifying in the future." (PMID 37996930, 2023).
myopia (1 paper, 2025). "However, why is ALKBH5 and FTO expression downregulated in nuclear cataract patients with high myopia?" (PMID 41315216, 2025). "Does high myopia lead to the downregulation of ALKBH5 and FTO expression by activating other signaling pathways?" (PMID 41315216, 2025). "Additionally, the expression of m6A-related enzymes, particularly the demethylases ALKBH5 and FTO, was downregulated, while methyltransferase METTL14 was upregulated in patients with high myopia." (PMID 41315216, 2025).
ocular melanoma (1 paper, 2025). A melanoma that arises from the structures of the eye or ocular adnexa. "In addition to YTHDF1 and METTL3, which affect ocular melanoma by influencing their downstream target genes, FTO has also been found to play a key role in ocular melanoma." (PMID 41315216, 2025).
oligospermia (1 paper, 2023). Decreased number of spermatozoa in the semen. "In addition, we identified two functional mutations of FTO in oligospermia and nonobstructive azoospermia (NOA) patients." (PMID 37146971, 2023).
Oncocytoma (1 paper, 2021). "FTO and ALKBH5 transcript levels were significantly higher in ccRCC compared to oncocytoma (p = 0.0088 and p < 0.0001, respectively)." (PMID 34683137, 2021). "In summary, we showed that FTO and ALKBH5 are differentially expressed among different RCC subtypes and oncocytomas, eventually proving useful for discrimination between malignant and benign renal cell tumors, as well as for prognostic assessment." (PMID 34683137, 2021). "ALKBH5 and FTO transcript and protein expression were evaluated in a series of primary RCC (n = 120) and 40 oncocytomas selected at IPO Porto." (PMID 34683137, 2021). "FTO and ALKBH5 immunostaining significantly differed between RCC subtypes and oncocytomas (including detailed statistical analysis)." (PMID 34683137, 2021). "Interestingly, ccRCC displayed higher FTO and ALKBH5 mRNA levels compared to other RCC subtypes, which were able to discriminate ccRCC from oncocytomas." (PMID 34683137, 2021). "In IPO Porto’s cohort, FTO and ALKBH5 transcript levels discriminated ccRCC from oncocytomas." (PMID 34683137, 2021). "Furthermore, FTO and ALKBH5 immunoexpression differed among RCC subtypes, with higher expression levels found in ccRCC comparatively to the other RCC subtypes and oncocytomas." (PMID 34683137, 2021). "Considering the role of m6A modification and its erasers in carcinogenesis, we hypothesized that demethylating enzymes, FTO and ALKBH5, might be potential biomarkers with distinct roles in different RCC subtypes and oncocytomas." (PMID 34683137, 2021). "Thus, FTO and ALKBH5 expression alterations found among different RCC subtypes and oncocytomas do not seem to derive from copy number variations." (PMID 34683137, 2021).
Oppositional defiant disorder (1 paper, 2012). An enduring pattern of uncooperative, defiant, and hostile behavior towards authority figures that does not involve major antisocial violations, is not accounted for by the child's developmental stage, and results in significant functional impairment. "We explored the association between FTO at rs9939609, symptoms of ADHD and symptoms of Oppositional Defiant Disorder (ODD) at the age of 3 years." (PMID 23155456, 2012).
oral epithelial dysplasia (1 paper, 2023). "Moreover, the role of FTO and ALKBH5 in oral precancerous lesions, especially in oral epithelial dysplasia (OED), has never been studied." (PMID 36582218, 2023).
oral lichen planus (1 paper, 2025). Oral lichen planus is a chronic inflammatory oral condition of unknown aetiology characterized by T-cell-mediated chronic immune response and abnormal epithelial keratinization cycle. "RNA m6A demethylase FTO plays critical regulatory roles in oral lichen planus development." (PMID 39995976, 2025). "Targeting FTO might be a promising therapeutic approach to prevent or manage oral lichen planus." (PMID 39995976, 2025). "However, the roles of FTO in the context of oral lichen planus (OLP) remain unknown." (PMID 39995976, 2025).
osteomyelitis (1 paper, 2025). An acute or chronic inflammation of the bone and its structures due to infection with pyogenic bacteria. "The m6A RNA methylation regulator FTO may serve as a potential diagnostic marker and therapeutic target, involved in the pathogenesis of S. aureus infection-related osteomyelitis." (PMID 39980685, 2025). "To further investigate the regulatory mechanism of FTO in macrophages during S. aureus-induced osteomyelitis, we utilized small interfering RNA (siRNA) technology to knock down FTO expression." (PMID 39980685, 2025). "Although the significance of FTO and other m6A-related genes in inflammatory diseases is known, research on their roles in S. aureus infection-related osteomyelitis remains limited." (PMID 39980685, 2025). "In conclusion, our study highlights the crucial role of the m6A RNA methylation regulator FTO in S. aureus infection-related osteomyelitis." (PMID 39980685, 2025). "This raises the possibility that FTO could play a critical role in the pathogenesis of S. aureus-induced osteomyelitis." (PMID 39980685, 2025).
osteonecrosis (1 paper, 2022). A none disease characterized by death of bone tissue due to a lack of blood supply. "The study aimed to evaluate the correlation between FTO polymorphisms and the susceptibility of osteonecrosis of the femoral head (ONFH)." (PMID 35706030, 2022).
premature senility syndrome (1 paper, 2025). "Among them, the expression of FTO was downregulated considerably in individuals with premature senility syndrome." (PMID 40636284, 2025).
prostate adenocarcinoma (1 paper, 2022). "We demonstrated that FTO is downregulated in prostate adenocarcinoma, and the downregulation of FTO was negatively correlated with disease-free survival." (PMID 35397614, 2022).
prostate tumors (1 paper, 2022). "To determine the expression pattern of FTO in PCa, we calculated the transcriptomic profiles of PCa tumor samples and adjacent prostate tissues in the TCGA and GEO database (GSE6919), and found that FTO was significantly downregulated in prostate tumors." (PMID 35397614, 2022). "Results showed that the silencing of FTO effectively promoted the growth of prostate tumors, which was reflected in the significant increase in the volume and weight of tumor compared with the controls." (PMID 35397614, 2022).
renal neoplasia (1 paper, 2021). "Interestingly, the recent integrated molecular analyses of The Cancer Genome Atlas (TCGA) emphasized the metabolic deregulation in the several renal tumors, with erasers FTO and ALKBH5 specifically associated with metabolic reprogramming." (PMID 34683137, 2021). "Nonetheless, the role of FTO in the pathobiology of renal neoplasia remains elusive." (PMID 34683137, 2021).
scleroderma (1 paper, 2024). Scleroderma is a rare autoimmune connective tissue disorder characterized by abnormal hardening of the skin and, sometimes, other organs. "In a bleomycin (BLM)-induced scleroderma mouse model, overexpression of FTO led to reduced m6A and mRNA levels of TNC, resulting in the alleviation of mouse skin fibrosis." (PMID 39072324, 2024). "FTO/TNC may become a new target for the treatment of Scleroderma in the future." (PMID 39072324, 2024).
scoliosis (1 paper, 2023). A congenital or acquired spinal deformity characterized by lateral curvature of the spine. "After comparing the paraspinal muscles of patients with AIS and CS, we observed a downregulation in the expression of FTO in the concave paraspinal muscles of both types of scoliosis." (PMID 37408034, 2023). "The consistent paraspinal muscle features seen in AIS and congenital scoliosis, as well as the reversible pattern of muscle fibers and expression of FTO in AIS suggest that FTO may contribute to the muscle fiber remodeling secondary to scoliosis." (PMID 37408034, 2023). "Instead, FTO may contribute to the muscle fiber remodeling secondary to scoliosis." (PMID 37408034, 2023). "We found a positive correlation between the mRNA level of FTO and the fraction of type I fibers, and a negative correlation between the mRNA level of FTO and the Cobb angle of scoliosis." (PMID 37408034, 2023).
seminoma (1 paper, 2018). A radiosensitive malignant germ cell tumor found in the testis (especially undescended), and extragonadal sites (anterior mediastinum and pineal gland). "It will be interesting to deeply investigate the functions of FTO in seminoma carcinogenesis." (PMID 30719031, 2018). "The present study first revealed the role of RNA demethylase FTO in the regulation of chromosome instability and cell cycle progression in spermatogonia, thus giving novel insights into the role of RNA methylation in spermatogenesis and potentially, in seminoma progression." (PMID 30719031, 2018). "Therefore, our results suggested that FTO may play important roles in the progression of seminoma for the first time." (PMID 30719031, 2018).
skin aging (1 paper, 2025). The gradual irreversible changes in structure of skin that occur as a result of the passage of time.. "In this study, we described the downregulation of FTO in aging skin tissues and HDFs, revealing its crucial role as a protective factor in HDF senescence and skin aging, mediated through m6A modification." (PMID 40636284, 2025).
T-cell leukemia (1 paper, 2025). A malignant disease of the T-lymphocytes in the bone marrow, thymus, and/or blood. "The RNA m6A demethylase FTO represents a promising therapeutic target in T cell leukemia." (PMID 40435251, 2025). "With several FTO inhibitors advancing to clinical stages, our findings suggest that these small-molecule drugs could be exploited for the treatment of T cell leukemia." (PMID 40435251, 2025).
testicular cancer (1 paper, 2021). A primary or metastatic malignant neoplasm that affects the testis. "Removing the SNP in the FTO gene did not alter the observed associations except for testicular cancer." (PMID 32895918, 2021).
tuberculosis (1 paper, 2014). A chronic, recurrent infection caused by the bacterium Mycobacterium tuberculosis. "This is the first study, to our knowledge, revealing the effect of genetic variations of intron 1 SNP rs9939609 of FTO on the risk of tuberculosis." (PMID 25377722, 2014). "Taken together, our results suggest that the FTO rs9939609 genetic polymorphism and the haplotype (rs9939609A-rs8050136C) are involved in the risk of tuberculosis in the Chinese population." (PMID 25377722, 2014). "This case-control study investigated the association between genetic polymorphisms of the FTO gene and tuberculosis in a Chinese Han population." (PMID 25377722, 2014). "Further work with both knockout and overexpression models of FTO and neighboring genes is likely to provide the most fruitful approach to understand the mechanisms and pathways through which these variants influence the risk of tuberculosis." (PMID 25377722, 2014). "We hypothesize that the FTO gene may play an important role in the risk of immune-related human infectious diseases such as tuberculosis." (PMID 25377722, 2014). "In the present study, we observed the role of common FTO rs9939609 SNP in the risk of tuberculosis, which supports the hypothesis that genetic polymorphisms of the FTO gene affect the host's susceptibility to infectious diseases." (PMID 25377722, 2014).
uremia (1 paper, 2023). A clinical syndrome associated with the retention of renal waste products or uremic toxins in the blood. "For example, METTL3 can be used as a therapeutic target and as an early diagnostic indicator of kidney diseases such as ischemia‒reperfusion injury, cisplatin-induced AKI and obstructive nephropathy; the demethylase FTO can be used as a therapeutic target for DN and uremia." (PMID 38066436, 2023).
Ureteral obstruction (1 paper, 2016). Obstruction of the flow of urine through the ureter. "Deficiency of the FTO gene attenuates the fibrogenic responses induced by ureteral obstruction in the kidney." (PMID 26727661, 2016). "Indeed, global gene transcriptions amplitude is reduced in FTO deficient kidneys after ureteral obstruction." (PMID 26727661, 2016). "To investigate the role of FTO in kidneys, we first analyzed the FTO protein abundance and mRNA expression levels in the kidneys after unilateral ureteral obstruction (UUO)." (PMID 26727661, 2016). "FTO is indispensable for the extracellular matrix synthesis after ureteral obstruction in kidneys." (PMID 26727661, 2016).
urinary system tumors (1 paper, 2023). "What is the role of FTO in promoting or inhibiting cell division, proliferation and invasion in urinary system tumors, and what role does it play in tumor genesis and development?" (PMID 37701836, 2023).
vitamin D deficiency (1 paper, 2015). A nutritional condition produced by a deficiency of VITAMIN D in the diet, insufficient production of vitamin D in the skin, inadequate absorption of vitamin D from the diet, or abnormal conversion of vitamin D to its bioactive metabolites. "The main finding of our study is that patients with a preoperative vitamin D deficiency lost more weight following RYGB surgery when they carried two copies of FTO rs9939609 A-allele, than their homozygote counterparts did, i.e., TT carriers who had a vitamin D deficiency." (PMID 25724814, 2015).